ID3 (inhibitor of DNA binding 3)
Diseases named in the same sentence as ID3 in open-access papers (continued):
Sharing a sentence is not in itself a finding about the gene and the disease.
tumor (continued). "A recent study found that Id3 inhibits the exhaustion of CD8 T cells in the tumor microenvironment (TME)." (PMID 35983065, 2022). "Previous research has shown that tumor xenograft neurogenesis, angiogenesis, and vascularization are dependent on Id1 and Id3, and Id3 is especially crucial for tumor angiogenesis." (PMID 35599595, 2022). "In TNBC, ID1 and ID3 are requisite for self-renewal, metastasis, tumor re-initiation, and colonization, making them attractive targets for cancer stem cell therapy." (PMID 36207293, 2022). "We selected 118 S100P-SPP1 + iCCApps from our TMA cohort to explore the prognostic values of ID3 + tumor cells and PDGFRβ + stromal cells (most of which were CAFs)." (PMID 35347134, 2022). "A future comprehensive identification and stratification of tumor entities characterized by aberrant ID3 expression will be necessary to enable anticancer clinical trials with PARP-inhibitors." (PMID 34718742, 2021). "ID1 and ID3 would be necessary for TIC (tumor-initiating cell) functions in the genesis of both primary tumors and metastases, sustaining proliferation via p21." (PMID 34295890, 2021). "Mechanistically, ID3 exhibits tumor suppressor functions in PTC cells by interacting with E47 to form heterodimers that prevent E47 binding to CDH1 promoter and maintaining CDH1 transcription and epithelial phenotype in PTC cells." (PMID 34462424, 2021). "To identify the role of low ID3 expression in tumors, we used TCGA gene expression data of cancer patients with different primary tumor entities." (PMID 34718742, 2021). "Taken together, our study demonstrates that ID3 plays a tumor suppressor role in PTC and impedes metastasis by inhibiting E47-mediated epithelial to mesenchymal transition." (PMID 34462424, 2021). "We detected high mRNA expression of the four ID genes in all cell lines, including the non-tumor cell line 184A1, which indeed showed significantly higher expression of ID1 and ID3 than all the tumor cell lines (all p ≤ 0.03)." (PMID 33514024, 2021). "Highlighting these results, stratification of tumor patients with aberrant ID3 expression will allow new targeted and personalized therapeutic options to be applied." (PMID 34718742, 2021). "The obvious higher expression level of Id3 protein was detected in ESCC tumor tissues compared with adjacent normal tissues (p<0.01)." (PMID 32760207, 2020). "IHC analysis showed that 15% of 4T1 tumor cells express high levels of Id1, and 35% have intermediate levels of Id1 expression, whereas the expression of Id3 was found in most of the cells." (PMID 32766238, 2020). "Five and sixty percentage of cells in the Id1C3-Tag tumor were stained positive for Id1 and Id3 expression, respectively, as observed by IHC." (PMID 32766238, 2020). "In medulloblastoma the Id2 and Id3 proteins are overexpressed and promote tumor cell proliferation, whereas the Id1 protein has been found to be expressed in the tumor vessels, thus promoting tumor angiogenesis." (PMID 28122577, 2017). "Four of these genes (ARID1A, APC, CDKN2A, and ID3) showed significantly reduced protein expression in the majority of tumor samples, whereas the remaining four genes displayed changes only in a few tumors." (PMID 29109526, 2017). "ID3 is involved in tumor growth, invasiveness, metastasis, and angiogenesis, and was up-regulated in the SN-38 resistant BC cell lines." (PMID 26801902, 2016). "To investigate the ability of Id3 to suppress tumor growth in vivo, we injected A431 cells subcutaneously into mice and tracked tumor growth via in vivo imaging of GFP-expressing cells." (PMID 25693514, 2015). "In the mouse xenograft model, we show that Id3 significantly decreases tumor size by >30% via apoptosis." (PMID 25693514, 2015).
tumor (continued). "ID1 and ID3 are essential for angiogenesis and neurogenesis during development and tumor growth, with ID1+/− ID3−/− knockout mice unable to support the growth of tumors." (PMID 25207642, 2014). "Some previous studies have demonstrated that both Id1 and Id3 promoted malignant progression of certain types of cancers through facilitating angiogenesis, a crucial feature of tumor development and progression." (PMID 25061504, 2014). "Our previous study showed that knockdown Id3 produced a reduction of 2.8- and 2.4-fold in average tumor weight and volume respectively." (PMID 25061504, 2014). "The weight of tumor in the Id1-suppressed group was dramatically decreased by 4.1- and 6.6-fold, and that in the Id1 and Id3 double knockdown group by 6.8- and 10.9-fold." (PMID 25061504, 2014). "Expression levels are generally decreased in adult organs and are increased with inflammation and tumor formation where Id1 and Id3 have been shown to have a key role in promoting angiogenesis." (PMID 24516656, 2014). "In the present study, also for the first time, tumor cell blocks and cytology smears have been included for Id1 and Id3 immunostaining analysis." (PMID 23311395, 2013). "Inhibitor of DNA binding 1 (Id1) and 3 (Id3) genes have been related with the inhibition of cell differentiation, cell growth promotion and tumor metastasis." (PMID 23311395, 2013). "We also found that tumor cells in PDICs specifically were positive for Id3, another Id family member which can play a redundant role to Id1." (PMID 23691228, 2013). "A comparison of Id1 and Id3 expression between primary tumor and matching metastatic tissues should be also investigated." (PMID 23311395, 2013). "As shown in a bone marrow transplant model with Id1+/-Id3-/- tumor-resistant mutant mice, transplanted bone marrow endothelial and hematopoietic precursor cells are fully capable of supporting tumor growth." (PMID 23676470, 2013). "In conclusion, the present study suggests that the tumor co-expression of Id1 and Id3 can be a powerful prognostic biomarker in a selected subgroup of stage III-N2 NSCLC patients receiving definitive chemoradiotherapy." (PMID 23311395, 2013). "We have studied, using monoclonal antibodies for immunohistochemistry, the Id1 and Id3 tumor epithelial expression in 17 patients with stage III-N2 non-small cell lung cancer (NSCLC) treated with definitive chemoradiotherapy." (PMID 23311395, 2013). "More interestingly, the co-expression of both proteins Id1 and Id3, in the same tumor samples, showed a significant inverse correlation with OS in those patients showing a clinical stage considered of worse prognosis (cT4N2 disease)." (PMID 23311395, 2013). "Surprisingly, Id3−/− mouse were shown to develop γδ T-cell lymphoma, suggesting a tumor suppressive role, at least in hematological malignancies." (PMID 23342268, 2012). "The tumor-promoting properties of Id1, Id2, and Id3 are at least partially shared by Id4 also: Id4 has been shown to promote neoplastic transformation/growth." (PMID 23342267, 2012). "Contrary to these observations, studies have also demonstrated pro-tumor function of Id4 that is consistent with its other family members Id1, Id2, and Id3." (PMID 23342267, 2012). "This statement is consistent with the fact that conditioned media obtained from distinct tumor types with unique patterns of metastatic spread redirected premetastatic niche formation, thereby transforming the metastatic profile, in Id3 knockout mice." (PMID 22433180, 2012). "The role of EPCs in tumor neovascularization was studied in an Id1 +/- Id3-/- mouse model which is tumor resistant and has defective angiogenesis, where transplantation of wild type bone marrow to the mutant mice restored tumor angiogenesis and growth." (PMID 21609465, 2011). "In various forms of tumours, Id1 and Id3 are overexpressed extensively and in an overlapping pattern." (PMID 20842131, 2010).
tumor (continued). "We demonstrated that intracellular-delivered Id1/3-PA7 colocalised to Id1 and Id3 and promoted increased expression of the tumour suppressor CDKN2A in a dose-dependent manner." (PMID 20842131, 2010). "Previously, we reported that tumor growth was inhibited more effectively in Id1+/−, Id3−/− than in Id1+/−, Id3+/+ mice." (PMID 19956687, 2009). "ID3, in particular, plays a crucial role in immune evasion and tumor progression." (PMID 40607387, 2025). "Furthermore, the role of ID3 in immune evasion and tumor proliferation underscores its potential as a therapeutic target, providing new avenues for immune checkpoint regulation and personalized treatment strategies." (PMID 40607387, 2025). "Knockdown of Id1 and Id3, either individually or in combination, from a cell line representative of the TN human subgroup of breast cancer resulted in partial or complete inhibition of the tumor-initiating capacity, respectively." (PMID 41303422, 2025). "However, the tumor-suppressive role of ID3 in tumor initiation and other related malignant behaviors requires further exploration." (PMID 40819127, 2025). "Additionally, Id1 and Id3 also play a role in the tumour immune microenvironment by supporting cancer cell stemness, limiting CD8+ T cell responses, and promoting an immunosuppressive environment." (PMID 39676870, 2024). "Moreover, we show that enforced expression of ID3 in other mouse and human macrophages such as iPSC-Macs is also sufficient to endow them with the ability to mount this anti-tumour response." (PMID 38326607, 2024). "First, RT-qPCR was used to assess ID1 and ID3 expression in BM tumour cells." (PMID 39676870, 2024). "Expression of ID3 is therefore necessary and sufficient to endow macrophages with the ability to form an efficient anti-tumour niche, which could be harnessed for cell therapy in cancer." (PMID 38326607, 2024). "In both cases, KCs represented the majority of macrophages in normal liver, but a minor subset in tumoural liver, and expressed higher ID3, lower SIRPA and higher chemokine (CCL4, CCL3) and cytokines genes (IL18) in comparison to CD14+TIM4− tumour-associated macrophages." (PMID 38326607, 2024). "Recently, ID3 expression was found to program effective anti-tumour macrophages." (PMID 39399500, 2024). "Conversely, knockdown of ID3 dampened anti-tumour control and hampered T cell function." (PMID 39399500, 2024). "It is crucial to highlight that both ID1 and ID3 play central roles in cancer biology, acting as transcriptional regulators that exert their influence on the intracellular transcriptional machinery of tumour cells." (PMID 39676870, 2024). "Additionally, loss of ID3 leads to an increase in the CD4 Th9 phenotype, exhibiting potent antitumour immunity, and adoptive TIL therapy using tumour specific CD4 Th9 cells demonstrates potent antitumour activity." (PMID 39676870, 2024). "It found that CD52 and ID3 were broadly dispersed throughout the four tissue samples, with a relatively low level of sparse distribution in the normal tissue region and a relatively high level of sparse distribution in the tumor region." (PMID 39256364, 2024). "In summary, here we show that ID3 is a master regulator of the immune response to cancer that is necessary and sufficient to orchestrate a potent local macrophage-driven anti-tumour response, and could be harnessed for the treatment of cancer." (PMID 38326607, 2024). "Therefore, it would be helpful to investigate the expression of ID3 in early and advanced tumors to understand the relationship between ID3 expression and tumor response." (PMID 37170184, 2023). "Conversely, degradation of ID3 gene increased MB cell apoptosis and impaired tumor cell migration." (PMID 37835380, 2023). "Similarly, several genes responsible for T-cell differentiation such as rag1 and id3 were downregulated in DN stage of tumor samples." (PMID 35504924, 2022).
tumor (continued). "Interestingly, one of the most significantly downregulated genes in DN cells was id3, which was expressed in preleukemic samples but almost completely suppressed in tumor samples." (PMID 35504924, 2022). "The ID3 gene encodes the DNA-binding protein inhibitor ID-3, which is a helix-loop-helix protein involved in negatively regulating the DNA-binding transcription factor TCF3 and behaves as a tumor suppressor." (PMID 33801781, 2021). "However, the tumor-suppressive effects of ID3 in tumor initiation and other malignant-related biological behaviors still require further exploration." (PMID 34462424, 2021). "Taken together, these data suggest that ID1 and ID3 may play roles in multiple stages of tumor growth and metastasis by regulating different processes in attached versus detached cancer cells." (PMID 32661241, 2020). "This phenotype would have mesenchymal features, that would result as a downstream effect of the STAT3-RAS-MAPK-ERK-MYC pathway, regulating ID3/E47 interactions and promoting tumor cell migration and invasion through expression of mesenchymal genes such as MMPs, SNAIL1, TWIST1, and PRRX1." (PMID 30899759, 2019). "Moreover, ID1 and ID3 are required for angiogenesis and vascularization of tumor xenografts, necessary for macro-metastasis development." (PMID 30899759, 2019). "Moreover, Id1 and Id3 endow tumor cells with stemness properties, thereby contributing to cancer initiation in vivo." (PMID 30297743, 2018). "Id1/Id3 expression promotes stemness properties and tumor initiation." (PMID 30297743, 2018). "It has been proposed that in androgen-dependent prostate cancers androgen might regulate proliferation, apoptosis and tumor suppression via Id1/Id3, Id2 and Id4 regulation, respectively." (PMID 28122577, 2017). "In contrast, lack of this regulation in androgen-independent cancers might lead to cell proliferation (Id1 and Id3 up-regulation), cell survival (Id2 down-regulation) and decreased tumor suppression (Id4 down-regulation)." (PMID 28122577, 2017). "Altogether, these data suggest that simultaneous high expression of ID1, ID3 and IGJ could be associated with poor prognosis in Hispanic adult B-ALL due to its potential to increase tumor cell survival possibly through NF-kB signaling." (PMID 27044543, 2016). "For example, ID family genes such as ID1 and ID3 have found to be deregulated in many types of human tumors and contribute to processes such as tumorigenesis, tumor progression, angiogenesis, cell migration, epithelial mesenchymal transition and stem cell renewal." (PMID 27044543, 2016). "This raises the possibility that Id1 and Id3 compensate for the function of Id2 in the duodenal- and jejunal-tumor initiation that is not affected by the loss of Id2." (PMID 26163528, 2015). "Similarly to Id1, Id3 expression was higher in DCs from tumour-bearing mice compared to DCs from control mice, however, Id3 expression levels in MDSCs from tumour-bearing mice were significantly lower compared to MDSCs from non-tumour-bearing mice." (PMID 25924227, 2015). "Thus, there is a link between the ability of Id3 to induce apoptosis and function as a tumor suppressor gene." (PMID 25693514, 2015). "We found that Id3 significantly reduces tumor size (≈33%, P = 0.002)." (PMID 25693514, 2015). "In a mouse xenograft model, Id3 induction decreased tumor size by 30%." (PMID 25693514, 2015). "Id1 and Id3 are highly expressed in endothelial cells in both developing and tumor blood vessels." (PMID 24516656, 2014). "The reduction in tumor sizes achieved in this study was obtained by reducing Id3 only." (PMID 25061504, 2014). "Id1 and Id3 are considered to have overlapping and synergistic functions in cancer biology and have been related with the inhibition of cell differentiation, cell growth promotion and tumor metastasis." (PMID 23311395, 2013).
tumor (continued). "Since Id3 was also expressed in these cells and may play a role in the proliferative and/or invasive phenotype of SGCs, it is possible that a double Id1/Id3 knockdown would further increase the reduction of tumor cell aggressiveness." (PMID 23517130, 2013). "Finally, peritoneal metastases of Id1/Id3 double-knockdown tumor cells were significantly reduced in a mouse model of peritoneal metastasis." (PMID 23311395, 2013). "The effect of ID3 knockdown on tumor seeding was observed in an animal model in vivo." (PMID 23768125, 2013). "However, in our study, the protein expression of TNC was generally limited to the tumor stroma, apart from tumor cell clusters where most of ID3 immunoreactivity was observed." (PMID 23768125, 2013). "Through a small array system and tumor cell line, we found several candidate genes of ID3 targets." (PMID 23768125, 2013). "Because of the wide range of ID3 expression levels in patients with tumor seeding, ID3 expression levels were dichotomized into high and low expression levels (> 6.007-fold difference vs. ≤ 6.007-fold difference, respectively) relative to the expression level of normal cerebellum." (PMID 23768125, 2013). "The tumor suppressor role of Id4 appears to be unique as compared to other members of the Id gene family (Id1, Id2 and Id3) that may act as oncogenes or co-operating oncogenes in many cancers." (PMID 19500415, 2009). "These genes are involved in the regulation of immune/inflammatory response (Lgals1, Ptgds, Tff2, Ubd), tumor angiogenesis (Lgals1, Esm1, Ndrg1), epidermal growth factor signaling (Erbb4, Nrg1), response to tissue injury (Tff2, Vnn1), and gene transcription (Id3, Ifrd1)." (PMID 19340302, 2009). "In addition, ID3 showed decreased expression levels in several tumour types such as ovarian adenocarcinomas." (PMID 18513385, 2008). "Therefore, hyaluronidase may reduce the expression of Id1 and Id3 proteins, potentially helping to mitigate tumor progression." (PMID 41208334, 2025). "We therefore reasoned that ID3 may regulate the inhibitory/activating receptor balance in macrophages, and that the control of SIRPA and dectin-1 expression may underlie at least part of the anti-tumour activities of wild-type KCs." (PMID 38326607, 2024). "Additionally, the ID3‐dependent anti‐tumor ability of KCs can be extended to other macrophages." (PMID 39220104, 2024). "We therefore sought to identify the molecular-level mechanism by which ID3 may control Sirpa expression in KCs, test its potential physiological importance and investigate whether the same mechanism can endow other macrophages with anti-tumour activity." (PMID 38326607, 2024). "Genetic aberrations of Id3 suggest that it may function as a tumor suppressor." (PMID 25693514, 2015). "Thus, it seems biologically plausible that higher Id1 and Id3 tumor expression levels may reflect the hypoxic status of the neoplasm and therefore would explain the radioresistance observed in those patients." (PMID 23311395, 2013). "Therefore, we suggest that Id1/3-PA7, as inhibitor of Id1 and Id3, could have the potential to be used as a new tool for targeted tumour therapy." (PMID 20842131, 2010). "To compare the effect of TCF7, ID3 and FOXO1 overexpression in vivo we treated OVCAR-3 tumour-bearing mice with Lewis Y CAR T cells." (PMID 38600376, 2024). "Consistent with low WNT signaling in RevCSCs, BLM tumor stem cells had decreased expression of WNT/stemness-related genes compared to Min tumors such as Axin2, Id2, Sox4, Wnt6, Wnt10a, Id3, Prox1, and Id1." (PMID 38893159, 2024). "Protein-coding genes with increased expression across all tumor types included E2F7, ETS1, EZH2, ID3/4, MKI67, PIK3R3, and TOP2A." (PMID 36865335, 2023). "Tumor cells from P09 and P10 were selected for this analysis as they contained a comparable number of ALB + and ID3 + cells." (PMID 35347134, 2022). "In contrast, ID3 + cells highly expressed genes such as MDK, ZEB1, and LGR5 that play important roles in tumor stemness." (PMID 35347134, 2022).